MLANA (melan-A)
Diseases named in the same sentence as MLANA in open-access papers (continued):
Sharing a sentence is not in itself a finding about the gene and the disease.
melanoma (continued). "In cases of pigmented EPC with atypical clinical and dermoscopical characteristics, immunohistochemical markers such as HMB-45, Melan-A and PRAME (Ab219650) may be used towards a differentiation from melanocytic lesions, including melanoma." (PMID 37189532, 2023). "Diagnosis is challenging and requires immunohistochemical confirmation of tumor cells expressing S-100, HMB-45, and Melan A. The immunohistochemical results of our patient did not support a diagnosis of malignant melanoma." (PMID 37273008, 2023). "Melan-A, MITF, andHMB45 can aid in distinguishing MPNST from carcinomas and melanomas." (PMID 36831419, 2023). "Furthermore, among the top 25 genes highly correlated with GREB1 gene expression in melanoma, 16 genes were known targets of MITF, such as MLANA and PMEL." (PMID 37658191, 2023). "In a phase IIa clinical study in stage III-IV melanoma patients, Imiquimod in combination with the MelQbG10 vaccine, which contains virus-like nanoparticles loaded with the TLR9 agonist CpG and Melan-A/MART-1 peptide, led to an increase in the frequency of central memory CD8+ T cells." (PMID 35651800, 2022). "Cells re-isolated from OS-REp via trypsin were positive for the keratinocyte marker cytokeratin 14 and negative for the melanoma marker Melan-A." (PMID 36175453, 2022). "The non-immune cell clusters were made up of melanoma cells (MLANA, PMEL, MITF, DCT), endothelial cells (VWF, PECAM1) and fibroblast cells (COL1A1, COL3A1)." (PMID 36433984, 2022). "On the other hand, distinction from melanoma is assessed by the absence of expression of Melan A and HMB45." (PMID 35637541, 2022). "Although our results need to be validated, they support the adoption of HMB45/PRAME, alone or in combination with PRAME and Melan A/PRAME, as a helpful marker in the diagnosis of melanocytic neoplasms with a high concordance rate between primary melanoma and corresponding metastases." (PMID 34508017, 2022). "Thus, for early-stage patients with a low immune score, the OS of melanoma patients with tumors of high SOX10 (Wald test, p = 0.0012) or MLANA (Wald test, p = 0.0051) was worse than that of those with low levels of SOX10 or MLANA." (PMID 35058553, 2022). "The IHC profile of these tumors shows positivity for a range of markers: S100 (nuclear marker; sensitive for melanoma), SRY-box transcription factor 10 (SOX10; nuclear marker; highly specific for melanoma), human melanoma black 45 (HMB45; cytoplasmic marker), and Melan-A (cytoplasmic marker)." (PMID 36289768, 2022). "Immunohistochemical staining shows a positive reaction to melanoma‐associated markers such as SOX10, HMB‐45, HMB‐50, Melan A, MITF, and NKI‐C3 and myogenic markers like SMA, but not to epithelial markers such as cytokeratin." (PMID 36056704, 2022). "Together, our data revealed significant interaction and an additive effect of the prognostic value of SOX10, confirmed by another melanoma marker MLANA, with an immune score in early- but not late-stage melanoma." (PMID 35058553, 2022). "The current case was negative for Melan-A and S100, which ruled out the likelihood of malignant melanoma." (PMID 34996495, 2022). "Vitiligo and antitumor responses in melanoma reportedly depend on CD8+ T cells that recognize identical antigens, so-called melanocyte/melanoma-shared antigens (MSA), including Melan-A, tyrosinase, and premelanosome (PMEL), and can reduce melanoma mass and prevent tumor recurrence." (PMID 35432377, 2022). "Neoplastic cells express PS100 in 50–70% of the cases, negativity for HMB45 and melan-A allows to rule out a melanoma." (PMID 35637541, 2022). "The expression of differentiation antigens that are commonly present and have been previously used as immunological targets in melanoma, namely, TYR (tyrosinase) and MLANA (Melan-A/MART1), were compared with CTAG1A and ROPN1 or ROPN1B in our panel of melanoma cell lines." (PMID 33918976, 2021).
melanoma (continued). "Based on results, the type of malignant melanoma also plays a role in influencing fluorescence, but regardless of the positivity or negativity of the markers Melan A and HMB-45." (PMID 33668679, 2021). "We further evaluated the gene expression levels of ROPN1, ROPN1B, CTAG1B (identical gene copy to CTAG1A for which no gene expression data is available), TYR and MLANA in 472 additional melanoma samples using data accessible via The Cancer Genome Atlas (TCGA)." (PMID 33918976, 2021). "These nanoparticles induced strong peptide-specific CD8+ T cell responses and anti-tumour activity in a B16.F10 melanoma model, and in PBMCs from healthy donors and melanoma patients, induced proliferative CD8+ T cell responses against the tumour antigen Melan-A." (PMID 36845569, 2021). "In conclusion, these results showed that therapeutic T-cell infused to P5 patient, who exhibited a partial response displayed the best profile, both in terms of functional avidity of Melan-A and MELOE-1 specific T cells and of reactivity against target melanoma cells expressing the two antigens." (PMID 34120214, 2021). "Four known melanoma cell marker genes, MITF, MLANA, PMEL and TYR, were obtained from CellMarker." (PMID 34784909, 2021). "Staining is positive for CD68 and vimentin and negative for Melan-A, human melanoma black (HMB)-45, S100 protein, pan-cytokeratin (CK), and actin." (PMID 34449582, 2021). "We assessed expression of ROPN1B, NY-ESO-1 (single protein from CTAG1A or CTAG1B genes), MLANA and SOX10 (used here as a melanoma tumour marker) at the protein level by multispectral immunohistochemistry on melanoma tissue microarrays (TMAs) comprising two or three cores from 61 patient tumours." (PMID 33918976, 2021). "CAFs were isolated from a cutaneous MM biopsy and were characterized: cells showed a spindle-shape and flattened morphology, and were strongly positive for vimentin and PDGFRβ according to the literature but were negative for the melanoma marker Melan-A." (PMID 34638245, 2021). "Here, CTCs were defined as positive for either pan-keratins for breast cancer and NSCLC or PMEL17/Melan-A-positive for melanoma samples, positive nucleus signal (DAPI) and negative for CD45 (leukocyte exclusion marker)." (PMID 34209696, 2021). "In addition to the amplitude of their specific T repertoires, Melan-A and MELOE-1 antigens were also selected on the basis of their frequent and shared expression by melanoma tumors, and regarding MELOE-1 antigen, for its strict tumor specificity." (PMID 34120214, 2021). "HMB-45, SOX10, and tyrosinase, but not melan-A, proved to differentiate the nevi from malignant melanomas successfully, with high specificity." (PMID 34206844, 2021). "S-100 protein, HMB-45, and Melan-A are usually positive in CCS and melanoma." (PMID 33478436, 2021). "Indeed, blood frequencies of Melan-A and MELOE-1 specific T cells are, respectively, around 10–4 and 10–5 among CD8 T cells in HLA-A*0201 melanoma patients, allowing their sorting from patient blood after a single step of peptide stimulation." (PMID 34120214, 2021). "Immunohistochemical markers used for diagnostic purposes of melanoma, e.g., HMB45 (gp100), tyrosinase, and Melan-A, are also often expressed in OcM and, thus, not able to distinguish between the different melanoma subtypes." (PMID 32718045, 2020). "We treated SB-3123p melanoma cells with either JQ1, BI-2536, Fenobam or PHA-793887 and found that the 4 compounds up-regulated the transcription of MITF and its target genes, DCT, Tyrp, Melan A and Pmel-1 in a dose dependent fashion as determined by qPCR." (PMID 32231230, 2020). "Nevertheless, the expressions of Melan-A, HMB45, and S-100 were positive in malignant melanoma." (PMID 32118771, 2020). "However, melanoma-related markers show relatively high expression, such as HMB45 (Figure 5B3) and melan-A (Figure 5B4)." (PMID 32150988, 2020).
melanoma (continued). "Melan A is a highly sensitive marker that is not expressed in the dendritic cells of lymph nodes like S100 is, which makes Melan A an appropriate candidate for melanoma detection in lymph nodes." (PMID 33339193, 2020). "Negative staining for cytokeratins and melanoma markers such as Melan-A, MITF, or HMB45 can be helpful in distinguishing MPNST from carcinomas and melanoma, respectively." (PMID 32642731, 2020). "S-100, HMB-45 and Melan-A are negative, thereby distinguishing the condition from malignant melanoma." (PMID 32532290, 2020). "Also, human melanoma black (HMB-45), Vimentin, and Melan A antibody are the melanocyte specific stains used for diagnosis of malignant melanoma." (PMID 32000450, 2020). "The melanin-laden cells were negative for two melanoma markers: the cytoplasmatic staining of Melan-A and the nuclear staining of SOX10." (PMID 32957691, 2020). "Both adrenocortical cancers and melanomas stain positive for Melan A, but adrenocortical tumors are negative for S100 (a positive marker for melanoma)." (PMID 32266384, 2020). "In concordance with this, it was observed that non-mutated melanoma associated antigens, MART-1/Melan-A, gp100, and tyrosinase, are heterogeneously expressed across melanoma cells." (PMID 33256089, 2020). "Choosing SCM as the microenvironment for melanoma cells was crucial with transcriptomic analysis that serum present in the medium drastically reduces expression of MITF-M and 74 MITF-dependent genes, including TYR, DCT, and MLANA." (PMID 31354817, 2019). "CLG isolated cells appeared epithelial, melanin rich, express the Melan A44 and S100 45 suggesting a melanoma cell line while EG isolated cells appeared negative for Melan A and S100." (PMID 31332163, 2019). "MITF level and expression of MITF-dependent pigmentation-related genes, MLANA, PMEL, TYR, and DCT, in drug-naïve and vemurafenib- or trametinib-treated patient-derived melanoma cell lines and their drug-resistant counterparts were analysed and referred to genomic alterations." (PMID 31354817, 2019). "Overall, with the exception of the single melan-A negative case, strong nBAP1 labelling was seen in each of the samples drawn from the most common anatomical sites to be affected by melanoma in the dog." (PMID 30060843, 2018). "Immunohistochemistry of Kdm2aa-deficient tumours with antibodies routinely used for clinical melanoma diagnoses revealed that they stained positive for Melan-A, but negative for two other melanoma markers S100 and HMB-45." (PMID 28806732, 2017). "Typically, melanoma cells are histologically characterized by the expression of S100, HMB45 and Melan A. The optimal treatment for melanoma remains undetermined, but surgery may be associated with a high cure rate for melanoma in situ." (PMID 27483468, 2016). "The protein S-100 is a very sensitive marker for melanoma (expressed in 95% of tumors) but it is not specific and should be used in combination with others markers such as Melan-A, HMB-45 and tyrosinase, which are much more specific (present in 70% of melanomas)." (PMID 27998306, 2016). "Furthermore, to obtain a more objective and quantitative measurement of micrometastasis, we assessed the gene expression of melanoma-related genes (MITF, MLANA, TYR and TYRP) in RNA extracts from lungs and livers of experimental groups." (PMID 27120788, 2016). "Common markers used to identify melanoma cell lines include: S100; HMB-45; and Melan-A." (PMID 27087056, 2016). "Spindle and epithelioid cell morphology with some degree of pleomorphism and increased mitotic count raised a suspicion of sarcoma or melanoma, but immunohistochemistry including desmin, CD 99, calretinin, and Melan-A was not supportive." (PMID 27747121, 2016). "In our previous study on melanoma, we observed a negative impact on survival for the patients who produced IL-4 reactive to Melan-A." (PMID 26500775, 2015).
melanoma (continued). "The high levels of telomerase activity in melanoma cells translated to strong expression of fluorescence after exposure to the viral probe and did not interfere with Melan-A expression." (PMID 25807549, 2015). "The resulting images of Melan-A positive cells stained in green color (B arrows) and the leukocytes stained in red color, showed no apparent cross reactivity of the melanoma markers with the leukocytes." (PMID 24811334, 2014). "Melanoma might share S-100 protein positivity, but also expresse other melanocytic markers, such as HMB45 and melan-A." (PMID 23388086, 2013). "Images representing immunostained melanoma tissue were then digitally processed to segment regions of interest, highlighting Melan-A positive and negative areas." (PMID 23690928, 2013). "Multifocal melanoma liver metastases were identified by lack of expression of cytokeratin, cytokeratin 19 and the expression of Melan A and vimentin." (PMID 23009723, 2012). "The immunohistochemistry has referred positivity in a varying level for the antigens related to the melanoma: NKI/C-3, S-100 protein, gp100 (HMB-45), Mart-1 (Melan-A), vimentin, tyrosinase and microphthalmia transcription factor (MiTF) that are useful in the diagnosis." (PMID 22143709, 2012). "Large numbers of melanoma-associated antigens (MAA) have been identified as well as the development of spontaneous T cell reactions and antibody production against various antigens (such as Melan-A, gp100, tyrosinase or NY-ESO-1) has been reported in patients with advanced melanoma." (PMID 24213320, 2012). "Further, as early-stage melanomas develop, immature melanocyte migration into the blood is somehow curtailed, whereas a significant proportion of patients develop elevated CTC levels (based on MIF and MLANA RNAs)." (PMID 22829910, 2012). "In addition, other genes known to be expressed in melanocytes, including MLANA, SILV, EDNRB and melanophilin, were also detected in these EGIR specimens overlying melanoma." (PMID 21294715, 2011). "Looking in depth at the peculiar features of TR-Melan-A interaction, we found a biased utilization of TRBJ1-5 segment and a 3-amino acid-long Glycine-Leucine-Glycine public motif occurring in several clonotypes of melanoma patients." (PMID 19317896, 2009). "On the contrary, no public TRB motifs were identified in the sequences of Melan-A-specific T cells of melanoma patients and controls." (PMID 19317896, 2009). "From an immunohistochemical point of view, S-100 protein, HMB-45, Melan-A, SOX-10, and MiTF are usually positive (melanocytic line differentiation features) and recently also it was demonstrated the potential utility of negativity for PRAME in the differential diagnosis with melanoma." (PMID 40004764, 2025). "Furthermore, using Melan A immunohistochemistry, we found an absence of pagetoid spread in 31% of nested melanoma and single cells in suprabasal epidermal layers in 69% of cases." (PMID 40941765, 2025). "Along the trajectory, the gene signature of cluster 3 in melanoma cells was characterized as the activation of certain functional pathways, including the cell adhesion pathway (VIM), immune response signaling pathway (JUN, EGR1), and melanosome organization signaling pathway (MLANA)." (PMID 38862482, 2024). "S100-P, HMB45, and Melan-A negativity in tumor cells ruled out a melanoma." (PMID 37218666, 2024). "Since genomic data were not suggestive of melanoma or any other specific entity, we focused our attention on sarcoma-specific genetic aberrations, particularly since clear cell sarcoma of soft tissue are often Melan-A positive, as well." (PMID 35501497, 2023). "Moreover, PRAME usually stains melanoma cells and is negative in non-tumoral melanocytes, in comparison with Melan-A and SOX10 that stain all melanocytes." (PMID 36980327, 2023). "The HS-Sch-2 cell line also stained negative for the melanoma marker Melan-A (data not shown)." (PMID 36818284, 2023).
melanoma (continued). "Melan-A-positive tumors with or without melanin pigmentation, consisting of infiltration of cells with epithelioid/spindle-shaped, hyperchromatic, pleomorphic nuclei and large eosinophilic nucleoli, were diagnosed as malignant melanoma." (PMID 35308701, 2022). "Transcript levels of conventional melanocytic markers (e.g. SILV, MLANA, and TYR) which are known to be dominantly regulated by MITF4,51, and of MITF itself were significantly inversely correlated with DNA methylation in the cell lines and TCGA melanoma samples." (PMID 35810190, 2022). "They then stimulated PBMCs of healthy donors with peptides from Melan-A/MART-1, a melanoma-specific tumor antigen, with or without a therapeutic dose of imatinib, and showed that imatinib treatment expanded Melan-A-specific CD8+ T cells accompanied by the depletion of eTregs." (PMID 34771599, 2021). "As the two members of the pan-melanoma cocktail, HMB-45 and tyrosinase, proved to differentiate benign vs. malignant lesions, together with SOX10, the present paper suggests that, in the conventional cocktail, melan-A should be substituted by SOX10, for a better differentiation." (PMID 33801642, 2021). "Indeed, this antigen, unlike Melan-A, had never been targeted in melanoma immunotherapy trials, and it was crucial to guarantee the safety of injecting T lymphocytes specific for this antigen." (PMID 34120214, 2021). "Cultures of melanocytes and melanoma cells obtained by this method are not contaminated by other cell types, and the cells retain their natural phenotypical features such as expression of tyrosine and Melan-A, as well as melanin production." (PMID 34944864, 2021). "We have not ascertained why the remaining case from a digital melanoma had only equivocal nBAP1 expression; however, this case also labelled negatively for melan A. This likely indicates a technical issue as this sample underwent decalcification, which is known to reduce antibody binding." (PMID 30060843, 2018). "However, with patient samples all cells were similar to each other with no clear size distinction between cells positive or negative for melanoma markers (either Melan A or S100B)." (PMID 24811334, 2014). "However, HMB45 and Melan A are usually positive in melanoma and negative for liposarcoma or osteosarcoma." (PMID 23082265, 2012). "Why some melanoma cells appear to express MLANA, but not TYR or MITF, is also not clear, but this hypothesis leads to the prediction that TYR and MITF levels will increase to control levels with time after removal of the melanomas." (PMID 22829910, 2012). "Metastatic melanoma with heterologous elements might enter the differential diagnosis since this will also be positive for Melan-A and negative for cytokeratin." (PMID 20687934, 2010). "Furthermore, no common motifs were found when Melan-A-specific sequences of melanoma patients were compared using particular BV or BVBJ combinations." (PMID 19317896, 2009). "human melanoma black -45 (HMB45)- and melan A-positive cells may be seen in pigmented neurofibroma." (PMID 19568560, 2009). "Notably, the Melan-A/MART1-specific CD8+ T cells isolated from vitiligo patients appear to possess an increased avidity and to exert a superior anti-tumor activity than those from melanoma." (PMID 16135249, 2005). "Additionally, we examined Melan A immunohistochemistry in our cohort to investigate pagetoid spread of melanocytes in the epidermis, as the existing literature reports that this highly specific melanoma criterion is often absent in nested melanoma." (PMID 40941765, 2025). "Furthermore, enforced expression of recombinant IL32α, -β, or -γ in M397 did not impact expression of melanoma differentiation genes MITF, AXL, NGFR or MLANA, strongly suggesting that IL32 is not a causal or upstream event in the melanoma dedifferentiation process." (PMID 30953519, 2019).